LPAR1 (lysophosphatidic acid receptor 1)
Diseases named in the same sentence as LPAR1 in open-access papers (continued):
Sharing a sentence is not in itself a finding about the gene and the disease.
pulmonary fibrosis (48 papers, 2009 to 2025). Chronic progressive interstitial lung disorder characterized by the replacement of the lung tissue by connective tissue, leading to progressive dyspnea, respiratory failure, or right heart failure. "LPAR1 has been implicated in several chronic inflammatory diseases, and especially pulmonary fibrosis, where it has been established as a promising therapeutic target." (PMID 40141453, 2025). "In vitro, we evaluated the activity of PIPE-791 using primary human lung fibroblasts whereby LPA addition induces COL1A1 production and promotes chemotaxis, two functions linked to LPAR1 activation and contribute to lung fibrosis." (PMID 40887574, 2025). "LPA also mediates fibroblast migration and proliferation via LPAR1 and is implicated in collagen gel contraction, a process associated with the development of pulmonary fibrosis." (PMID 38921452, 2024). "For example, in a bleomycin-induced lung fibrosis mouse model, lysophosphatidic acid receptor 1 (LPA1) deficiency resulted in a reduced level of fibroblast recruitment." (PMID 37923730, 2023). "Recent studies have demonstrated that lysophosphatidic acid (LPA) and its receptor lysophosphatidic acid receptor 1 (LPA1) are important causes of pulmonary fibrosis because LPA and LPA1 enhance the proliferation and viability of pulmonary fibroblasts." (PMID 35008524, 2021). "Here, we chose to focus our efforts on PCLS from donors diagnosed with pulmonary fibrosis, the underlying question being whether inhibiting LPAR1 in these slices with PIPE-791 would impact the expression of fibrosis-related mRNAs." (PMID 40887574, 2025). "Here, we have provided several lines of evidence in support of PIPE-791, a potent, orally bioavailable small molecule LPAR1 antagonist, as a treatment for lung fibrosis." (PMID 40887574, 2025). "Antagonists against the G-protein coupled receptor, lysophosphatidic acid receptor 1 (LPAR1) have shown efficacy in lung fibrosis preclinically and clinically." (PMID 40887574, 2025). "As such, we profiled PIPE-791, a potent, small molecule LPAR1-selective antagonist with uniquely favorable pharmacological kinetics, in various lung fibrosis contexts." (PMID 40887574, 2025). "Numerous selective ATX or LPAR1 inhibitors have been developed and so far, their clinical efficacy has only been evaluated in idiopathic pulmonary fibrosis." (PMID 36080255, 2022). "Several studies have suggested the potential value of LPAR1 inhibitors as a therapeutic strategy for lung fibrosis." (PMID 36577757, 2022). "LPAR1 has been previously explored as a target against pulmonary fibrosis because mice with LPAR1 knockout exhibit reduced lung fibrosis following the bleomycin challenge." (PMID 36577757, 2022). "Several LPAR1 antagonists have recently been evaluated in clinical trials for treating idiopathic pulmonary fibrosis and diffuse cutaneous systemic sclerosis, considering that the LPA and LPAR1 roles have been demonstrated in animal models and patients." (PMID 34302117, 2021). "Since the discovery that LPAR1 is overexpressed in samples from patients with idiopathic pulmonary fibrosis (IPF) and kidney fibrosis, several groups tried to target LPARs or ATX with small molecules to inhibit fibrosis." (PMID 33526777, 2021). "LPAR1 KO mice are protected from bleomycin-induced lung fibrosis by reducing the fibroblast activation and chemotaxis." (PMID 34302117, 2021). "Several LPAR1 antagonists have recently been included in clinical trials for the treatment of idiopathic pulmonary fibrosis and diffuse cutaneous systemic sclerosis." (PMID 34302117, 2021). "Lysophosphatidic acid receptor 1 (LPA1) is in the spotlight because its synthetic antagonist has been under clinical trials for lung fibrosis and psoriasis." (PMID 31429777, 2019). "Furthermore, the LPAR1/3 antagonist VPC12249 has been shown to alleviate pulmonary fibrosis in a mouse model of radiation-induced lung fibrosis." (PMID 38921452, 2024).
pulmonary fibrosis (continued). "To date, the LPAR1 inhibitors BMS-986020 and BMS-986278 have entered clinical trials for idiopathic pulmonary fibrosis, while the LPAR1 inhibitor SAR100842 has been included in clinical trials for reducing skin sclerosis in patients with diffuse cutaneous systemic sclerosis." (PMID 37372960, 2023). "LPAR1 knockout mice show a reduction in both renal and pulmonary fibrosis." (PMID 36577757, 2022). "While LPAR1 mRNA has been shown to be elevated in IPF donor lung tissue and in preclinical pulmonary fibrosis models, scant data around protein expression (particularly in human tissue) has been lacking." (PMID 40887574, 2025). "Having shown elevated LPAR1 expression in IPF tissue sections by autoradiography, we obtained cryopreserved PCLS tissue from normal donors and donors with pulmonary fibrosis." (PMID 40887574, 2025). "Together with the data presented here, as well as previous data showing LPAR1 involvement in IPF, we believe that there is a strong impetus for the development of PIPE-791 as a treatment for lung fibrosis." (PMID 40887574, 2025). "We also show that LPAR1 is elevated in IPF lung tissue and that PIPE-791 significantly reduced several markers of lung fibrosis in PCLS as measured by gene expression and secreted biomarkers." (PMID 40887574, 2025). "Two LPAR1 inhibitors, BMS-986020 and BMS-986278, are currently under clinical trial as innovative therapeutic agents for idiopathic pulmonary fibrosis (IPF)." (PMID 38921452, 2024). "In this context, genetic studies have demonstrated a decisive role of LPAR1 and ATX in mouse models of lung fibrosis." (PMID 36080255, 2022). "Specifically, LPA promotes fibroblast accumulation and vascular leak through LPAR1, whereas mice lacking the Lpar1 gene were protected from modeled pulmonary fibrosis." (PMID 40141453, 2025). "Expression of LPAR1 and 2 was implicated since bleomycin-treated mice lacking LPAR1 or LPAR2 were protected from developing lung fibrosis." (PMID 33794877, 2021). "Interestingly, several Gq-coupled GPCRs and their ligands are important drivers of pulmonary fibrosis, including PAR1, lysophosphatidic acid receptor 1, and endothelin receptors." (PMID 27549302, 2016).
ovarian carcinoma (25 papers, 2010 to 2025). A malignant neoplasm originating from the surface ovarian epithelium. "In ovarian cancer cells, LPAR1/3-GNAI2 mediates the LPA-stimulated activation of p130Cas, and this LPAR1/3-GNAI2-p130Cas signaling network is intimately associated with invasive migration of ovarian cancer cells." (PMID 27811362, 2016). "Conversely, ovarian cancer appears to be characterized by decreased LPAR1 expression and tumor aggressiveness is associated with altered LPAR 2 and LPAR3, LPAR3 being capable of signaling via Gi-proteins." (PMID 26701886, 2016). "Among the three LPA receptors, LPAR1 expression was strongly enhanced in ovarian cancer cells and significantly higher in 3D spheroids than that in adhered cells." (PMID 37596406, 2023). "This study intended to investigate the role and regulatory mechanism of miR-367 in ovarian cancer involving lysophosphatidic acid receptor-1 (LPA1)." (PMID 33024414, 2020). "In the Oncomine database, the results showed that LPAR1 was highly expressed in lymphoma while lowly expressed in prostate, bladder, brain, colon, head and neck, kidney, leukemia, lung, melanoma, and ovarian cancers." (PMID 32656075, 2020). "The ovarian cancer stem cell properties induced by LPA stimulation are abrogated by LPAR1-specific inhibitors or LPAR1 silencing." (PMID 31384176, 2019). "The data argue against LPAR1 and fibrosis as monotherapy targets for metastasis prevention in triple-negative breast cancer and ovarian cancer." (PMID 29805748, 2018). "Our in vitro data suggested that LPAR1 is the major receptor of LPA-induced ovarian cancer metastasis." (PMID 27809800, 2016). "In the present study, we focused on LPAR1-3 for their possible role in ovarian cancer cell invasion and metastasis, as these are the most characterized lines and their aberrant expression have been detected in various cancer tissues." (PMID 27809800, 2016). "We also tested the effects of LPAR1 inhibition or overexpression on ovarian cancer cell's invasiveness." (PMID 27809800, 2016). "High expression levels of LPAR1 were revealed in all the metastatic ovarian cancer cells (ES2, OVCAR429, HEY, OVCAR433, OVCAR5, SK-OV3, and OCC1)." (PMID 27809800, 2016). "Silencing LPAR1 impaired spheroid formation in ovarian cancer cells." (PMID 37596406, 2023). "When LPAR1 is overexpressed, it stops the tumor cell growth and migration in gastric cancer but promotes tumor occurrence and progression in the prostate and ovarian cancer." (PMID 36769510, 2023). "However, LPAR1 expression has also been reported to be significantly increased in other tumors, such as human hepatic cancer, osteosarcoma and ovarian cancer, and to exert tumor-promoting effects directly or mediated by chemotherapy resistance." (PMID 35884407, 2022). "While LPAR1–3 in general mediate LPA’s tumor promoting activities, limited reports showed that LPAR1 may represent a negative regulatory LPA receptor inducing apoptosis in ovarian cancer cells." (PMID 29987226, 2018). "Given that LPAR1/2/3 expression is linked to invasion and metastasis in different cancer types, we investigated the specific receptor subtype responsible for ETS‐1 regulation in ovarian cancer cells." (PMID 28236660, 2017). "The expressions of LPAR1-3 in different ovarian cancer lines were examined by qRT-PCR." (PMID 27809800, 2016). "LPAR1 acts as the main mediator responsible for LPA-stimulated ovarian cancer cell invasion." (PMID 27809800, 2016). "In summary, our study demonstrated that LPA response might be a prerequisite for peritoneal metastasis of ovarian cancer cells, and that LPAR1 is the major mediator for LPA-induced ovarian cancer invasion as well as metastasis." (PMID 27809800, 2016). "Besides, we demonstrated that LPAR1 acts as the main mediator responsible for LPA-stimulated ovarian cancer cell invasion." (PMID 27809800, 2016).
ovarian carcinoma (continued). "As multiple signaling pathways are involved in tumor cell migration, there may also be other key factors in signal transmission of ovarian cancer besides LPAR1." (PMID 27809800, 2016). "The expression of LPAR1-3 in different ovarian cancer lines was examined by qRT-PCR." (PMID 27809800, 2016). "High expression level of LPAR1 was detected in all of the metastatic ovarian cancer cell lines." (PMID 27809800, 2016). "Moreover, we observed that LPAR1 was highly expressed in all invasive ovarian cancer cells and all the three low LPAR1 expressing cells are non-invasive ones through there are still three of non-invasive lines expressing a moderate level of LPAR1." (PMID 27809800, 2016). "This analysis indicated that LPAR1 was highly expressed in lymphoma and lowly expressed in prostate cancer, bladder cancer, brain and central nervous system cancer, head and neck cancer, colorectal cancer, kidney cancer, lung cancer, leukemia, melanoma, and ovarian cancer." (PMID 32656075, 2020). "LPAR1, which is located upstream of the PI3K/AKT pathway, may present an effective target for the treatment of ovarian cancer." (PMID 31384176, 2019). "The qRT-PCR results showed that LPAR1, LPAR2, and LPAR3 were positive in 75.00 %, 12.50 %, and 6.25 % in the 15 of the normal ovarian specimens, respectively; and 69.23 %, 42.31 %, 17.31 % in the 52 of the ovarian cancer specimens, respectively." (PMID 27809800, 2016). "However, in our study, we demonstrated that LPAR1 expression in invasive ovarian cancer cells was significantly higher than in non-invasive ones; while the expression of LPAR2 and LPAR3 had no statistical correlation with the metastatic potential of ovarian cancer cells." (PMID 27809800, 2016).
prostate carcinoma (18 papers, 2013 to 2025). A carcinoma that arises from epithelial cells of the prostate gland. "Accumulated research has revealed the decreased expression of LPAR1 and its migration-inhibiting effects in tumors including prostate cancer, gastric cancer and pancreatic cancer, which is consistent with our results." (PMID 35884407, 2022). "LPAR1 was significantly downregulated in prostate cancer, and high LPAR1 expression was correlated with a favorable overall survival." (PMID 35884407, 2022). "LPAR1 activation was reported to stabilize acinar morphology and regulate cytoskeletal organization in prostate cancer cells." (PMID 34440828, 2021). "In prostate cancer cells, antagonist and knockdown experiments demonstrated that LPAR1 was the primary LPAR involved." (PMID 34440828, 2021). "Through the TIMER database, we found that LPAR1 impacted tumor-infiltrating immune cells in prostate cancer." (PMID 32656075, 2020). "Our findings offer deeper insights into the mechanisms of LPAR1 in the development of prostate cancer." (PMID 32656075, 2020). "TCGA datasets and the Oncomine database revealed that LPAR1 was significantly downregulated in prostate cancer." (PMID 32656075, 2020). "A high LPAR1 expression has a correlation with a low HR for poor prognosis, suggesting that LPAR1 is a critical biomarker in prostate cancer." (PMID 32656075, 2020). "To gain deeper insights into the tumor mechanisms in human prostate cancer, we performed analyses to reveal the relevance between LPAR1 and the prognosis of patients with prostate cancer." (PMID 32656075, 2020). "A set of papers indicated that LPAR1 is a prognostic biomarker in various cancers and takes an important part in the development of prostate cancer." (PMID 32656075, 2020). "Further molecular experiments are deserved to verify the mechanisms of LPAR1 and its effects on the clinical outcome in prostate cancer." (PMID 32656075, 2020). "We integrated chemokines and chemokine receptors and analyzed the association between LPAR1 and immune cell migration to explore the potential immune-related mechanisms of LPAR1 in prostate cancer." (PMID 32656075, 2020). "It has been made available in order to figure out the function of LPAR1 in prostate cancer at a large scale." (PMID 32656075, 2020). "In summary, LPAR1 is a potential prognostic biomarker and plays an important part in immune infiltrates in prostate cancer." (PMID 32656075, 2020). "Integrative analysis and several visualization methods were used in this present study to explore the mechanism of LPAR1 in prostate cancer." (PMID 32656075, 2020). "The findings suggested the potential mechanisms of LPAR1, giving us new insights into the important role of LPAR1 in prostate cancer." (PMID 32656075, 2020). "The present study suggests, based on bioinformatics analysis, the importance of LPAR1 in prostate cancer." (PMID 32656075, 2020). "The GSEA results showed that the LPAR1 function was enriched in GO_Leukocyte_Differentiation and GO_Lymphocyte_Mediated_Immunity in prostate cancer." (PMID 32656075, 2020). "CD97 was found to be involved in invasiveness and metastasis of prostate cancer, (where it forms heterodimers with the lysophosphatidic acid receptor LPAR1) and more recently of GBMs." (PMID 24662753, 2014). "The authors also showed that CD97 heterodimerizes and positively regulates lysophosphatidic acid receptor 1 (LPAR1) signaling, a well-established mediator of tumorigenesis and metastasis in prostate cancer." (PMID 23658650, 2013). "Furthermore, LPAR1 was reported to mediate migration- or invasion-inhibiting signals in prostate cancer, gastric cancer and pancreatic cancer." (PMID 35884407, 2022). "Interestingly, one report suggested that LPAR1 expression in androgen receptor-expressing prostate cancer cells is regulated in an androgen-dependent manner." (PMID 34440828, 2021).
prostate carcinoma (continued). "Patients with high LPAR1 expression had a prolonged OS time, suggesting that LPAR1 may be involved in the initiation and the progression of prostate cancer." (PMID 32656075, 2020). "It hints that LPAR1 improves the immune response of prostate cancer through various pathways." (PMID 32656075, 2020). "We found that LPAR1 impacted tumor-infiltrating immune cells in prostate cancer." (PMID 32656075, 2020). "LPAR1 was lowly expressed in prostate cancer and was significantly related to patient survival." (PMID 32656075, 2020). "Consequently, LPAR1 may play a critical role in regulating TME in prostate cancer by participating in cellular and humoral immunity and motivating the anti-tumor function." (PMID 32656075, 2020). "However, the correlation between LPAR1 and prognosis in prostate cancer, as well as the potential mechanism, remains unclear." (PMID 32656075, 2020). "Hence, LPAR1 is a potential immune-related biomarker in prostate cancer." (PMID 32656075, 2020). "Lastly, while we explored the role of GDPD3 in LPA/LPAR1/AKT signaling, further mechanistic studies are needed to fully elucidate its contribution to prostate cancer progression." (PMID 41562071, 2025). "This work examined events occurring in a human prostate cancer cell line three hours after the addition of LPA, a lipid growth factor that activates LPAR1 in these cells." (PMID 38396744, 2024). "Our previous work showed that 18:1-lysophosphatidic acid (LPA), which activates the G protein-coupled receptor LPAR1, induces CCN1 between 2–4 h in PC-3 human prostate cancer cells in a manner than enhances cell-substrate adhesion." (PMID 38396744, 2024). "Early on, LPAR1 was identified as the receptor mediating many of the stimulatory effects of LPA on the proliferation and migration of prostate cancer cells." (PMID 34440828, 2021). "LPAR1, LPAR2, and LPAR3 are expressed at varying levels in three commonly studied human prostate cancer lines, PC-3, DU145, and LNCaP." (PMID 34440828, 2021). "In prostate cancer cells, LPA receptor 1 (LPAR1) expression was sufficient to allow LPA-initiated migration and co-expression of CD97 and LPAR1 resulted in enhanced Rho-dependent invasion relative to LPAR1 alone." (PMID 26462154, 2015). "In addition, LPAR1 may be involved in the biological process when immune cells move into the tumor tissues and improve the TME of patients, which impact the development of prostate cancer and the prognosis of patients." (PMID 32656075, 2020).
idiopathic pulmonary fibrosis (16 papers, 2017 to 2024). Idiopathic pulmonary fibrosis (IPF) is a nonneoplastic pulmonary disease that is characterized by the formation of scar tissue within the lungs in the absence of any known cause. "Apart from cancer, LPAR1 antagonists, BMS-986020, and BMS-986278 focused on idiopathic pulmonary fibrosis (IPF) and aimed to prove the application of LPAR." (PMID 34209775, 2021).